RN7SL434P (RNA, 7SL, cytoplasmic 434, pseudogene)
Gene: Miscellaneous RNA gene on chromosome 3 (196,397,508 to 196,397,778, reverse strand). Ensembl gene ENSG00000241868.
Homologues: Orthologues: chimpanzee Metazoa_SRP (99% identical), macaque Metazoa_SRP (94% identical). Paralogues in human: RN7SL1 (83% identical), RN7SL2 (83% identical), RN7SL3 (82% identical), RN7SL122P (80% identical), RN7SL220P (80% identical), RN7SL230P (80% identical), RN7SL566P (79% identical), RN7SL191P (79% identical), RN7SL597P (79% identical), RN7SL709P (79% identical), RN7SL239P (78% identical), RN7SL296P (78% identical), and 699 more.